KNL1 (kinetochore scaffold 1)
Diseases named in the same sentence as KNL1 in open-access papers:
KNL1 is named in the same sentence as 50 diseases in open-access papers, as found by Europe PMC text mining. Sharing a sentence is not in itself a finding about the gene and the disease. The quoted sentences say what the papers report.
microcephaly (17 papers, 2015 to 2025). A congenital or acquired developmental disorder in which the circumference of the head is smaller than normal for the person's age and sex. "Defects in KNL1 function have been associated with genomic instability, leukemia, microcephaly, and neurological disorders." (PMID 36685823, 2022). "Applied en masse, as in Knl1 deletion, apoptotic elimination of these cells would lead to massive cell loss and microcephaly." (PMID 31197172, 2019). "Applied en masse following Knl1 deletion, however, they cause massive cell loss and severe microcephaly." (PMID 31197172, 2019). "KNL1 mutations cause microcephaly and KNL1 mediates the spindle assembly checkpoint, a safeguard against chromosome missegregation and aneuploidy." (PMID 31197172, 2019). "Consistent with this, there is evidence that microcephaly is caused by KNL1 mutations." (PMID 38693434, 2024). "These splice variants may act in the same manners as observed in the case of KNL1 splice variants and may explain the phenotype of isolated microcephaly." (PMID 36831309, 2023). "In addition to defining a new function for ancient chromosome-segregation machinery, our findings suggest new potential reasons for the rapid evolution of kinetochore proteins ( e.g., Knl1 in primates) and for the existence of human microcephaly mutations in Knl1." (PMID 30827898, 2019). "A second CASC5 mutation was identified in a consanguineous Pakistani family afflicted with MCPH and a recent paper reported the first case of an infant, with microcephaly associated with the mutated KNL1 gene, in an African American family." (PMID 31878213, 2019). "Earlier Knl1 deletion by Emx1-Cre led to microcephaly more severe than hGFAP-Cre and a loss of both deep and upper layer neurons." (PMID 31197172, 2019). "In hESC-derived NPCs, a KNL1 mutation (KNL1c.6125G > A) has been associated to aneuploidy, reduced proliferation, premature differentiation, apoptosis, and an abrogated spindle assembly checkpoint (SAC), culminating in microcephaly." (PMID 37881689, 2023). "iPSCs-derived cerebral organoids with mutations in genes KNL1 and NARS1 also displayed a reduction in neural progenitors and defect in the formation of neural rosette structure, which might be relevant to microcephaly." (PMID 34982276, 2022). "Consistent with this, microcephaly as a result of Knl1 deletion was partially alleviated in dKO." (PMID 31197172, 2019). "A conditional deletion of KNL1 using Cre recombination in cortical neural progenitor cells at E12.5 produced a 40% decrease in the cortical area at birth, which is consistent with the human microcephaly phenotype." (PMID 31878213, 2019). "Aneuploidy, therefore, may not be the singular underlying cause of severe microcephaly in patients with KNL1 mutations." (PMID 31197172, 2019). "Among these are KNL1, ASPM, and CITK, which are especially required during neurogenesis being extensively expressed in the VZ and SVZ, are known to induce the accumulation of DNA lesions and microcephaly when defective." (PMID 37881689, 2023). "We found that SAC disruption in Knl1 cKO led to microcephaly, but likely not as a direct result of aneuploidy." (PMID 31197172, 2019).
microcephaly (continued). "However, recent findings have demonstrated that Knl1-induced microcephaly in mice (Knl1fl/fl; hGFAP-Cre) is not a direct result of aneuploidy, but from the generation of missegregated chromosomes carrying DNA damage in the form of DSBs after SAC disruption." (PMID 37881689, 2023).
gastric cancer (7 papers, 2018 to 2023). A primary or metastatic malignant neoplasm involving the stomach. "Kinetochore scaffold 1 (KNL1) has been confirmed to be associated with the malignant behavior of colorectal cancer, lung adenocarcinoma, gastric cancer, and other tumor cells." (PMID 35389773, 2022). "In recent years, the high expression of KNL1 in cancer and related cases of promoting the occurrence and development of cancers such as colon cancer, gastric cancer and lung cancer have also been reported." (PMID 36685823, 2022). "For example, miR-193b-3p silencing promotes cell proliferation in gastric cancer through upregulating the expression of KNL1." (PMID 32795273, 2020). "In the present study, we analyzed the DNA sequencing data of 229 patients from the TCGA-STAD project and identified five potential driver genes (CCDC169-SOHLH2, TTN, KNL1, C6, NRXN1) whose mutations were negatively associated with gastric cancer recurrence (p < 0.01)." (PMID 35187167, 2022). "In recent years, more and more studies have shown that KNL1 dysregulation may lead to the progression of colorectal cancer and gastric cancer." (PMID 36685823, 2022). "Five mutated genes, KNL1, NRXN1, C6, CCDC169-SOHLH2, and TTN, showed a significant negative correlation with the recurrence of gastric cancer through multivariable logistic regression analysis." (PMID 35187167, 2022).
colorectal cancer (6 papers, 2022 to 2023). A primary or metastatic malignant neoplasm that affects the colon or rectum. "Increased KNL1 protein expression has been reported in colorectal cancer and is significantly associated with poor survival, whereas the effects of its downregulation included inhibition of cell proliferation and induction of apoptosis." (PMID 37445641, 2023). "Experiments have shown that KNL1 can inhibit the apoptosis of colorectal cancer cells and promote their proliferation." (PMID 36776306, 2023). "Evidence has shown that KNL1 plays an effective role in decreasing apoptosis and promoting the proliferation of colorectal cancer cells, and downregulation of KNL1 by miR-193b-3p significantly induces cell differentiation." (PMID 35187167, 2022). "A large number of previous studies have proven that KNL1 is crucial in the development of lung cancer, colorectal cancer and cervical cancer, but there is a lack of studies about the role of KNL1 in the development of UCEC." (PMID 36776306, 2023).
breast carcinoma (5 papers, 2002 to 2023). "Down-regulation of KNL1 can inhibit the growth and induce cell death of cervical cancer and breast cancer cells." (PMID 36685823, 2022).
lung adenocarcinoma (5 papers, 2020 to 2026). A carcinoma that arises from the lung and is characterized by the presence of malignant glandular epithelial cells. "Kinetochore scaffold 1 (CASC5, also named KNL1) is reported as an oncogene in lung adenocarcinoma and CRC." (PMID 37009050, 2023).
cervical cancer (3 papers, 2002 to 2023). A primary or metastatic malignant neoplasm involving the cervix. "Meanwhile, knockdown of KNL1 expression in cervical cancer HeLa cells inhibited their proliferation and induced apoptosis both in vivo and in vitro." (PMID 36776306, 2023).
leukemia (3 papers, 2002 to 2023). A malignant (clonal) hematologic disorder, involving hematopoietic stem cells and characterized by the presence of primitive or atypical myeloid or lymphoid cells in the bone marrow and the blood. "Additionally, kinetochore proteins like CENP-K and KNL-1 have been reported as fusion partners of MLL in leukemia." (PMID 37379335, 2023).
Primary microcephaly (3 papers, 2017 to 2023). Head circumference below 2 standard deviations below the mean for age and gender at birth. "To date, mutations in only two kinetochore members have been associated with human disease: KNL1 (CASC5, MIM:*609173) as cause of primary microcephaly and CENPE (MIM:*117143) as cause of profound microcephalic primordial dwarfism." (PMID 29228025, 2017).
prostate carcinoma (2 papers, 2020 to 2022). A carcinoma that arises from epithelial cells of the prostate gland. "Furthermore, qRT-PCR assay showed that KNL1 was highly expressed in five prostate cancer cell lines compared with normal cells." (PMID 36685823, 2022).
acute myeloid leukemia (1 paper, 2023). Acute myeloid leukemia (AML) is a group of neoplasms arising from precursor cells committed to the myeloid cell-line differentiation. "Similarly, the expression of KNL1 was decreased in kidney renal clear cell carcinoma (KIRC), kidney renal papillary cell carcinoma (KIRP), acute myeloid leukemia (LAML), and testicular germ cell tumors (TGCTs) compared to normal tissues." (PMID 36776306, 2023).
asthenospermia (1 paper, 2023). "In conclusion, we established an association between KNL1 and male fertility, providing a guide for future genetic counseling regarding oligospermia and asthenospermia, and a powerful method for further exploring spermatogenic dysfunction by utilizing flow cytometry and immunofluorescence." (PMID 36904774, 2023). "Here, we first linked KNL1 to male reproductive health and the loss-function of KNL1 resulted in oligospermia and asthenospermia in mice (an 86.5% decrease in total sperm number and an 82.4% increase in static sperm number, respectively) through CASA (computer-aided sperm analysis)." (PMID 36904774, 2023).
Azoospermia (1 paper, 2023). Absence of any measurable level of sperm,whereby spermatozoa cannot be observed even after centrifugation of the semen pellet. "Thus, it could be summarized the loss-function of KNL1 leads to oligospermia and azoospermia in mice and cause harm to male reproduction." (PMID 36904774, 2023).
brain tumor (1 paper, 2021). "In conclusion, inhibition of KNL1, CENPE, ASPM, CITK, and KIF14 may mimic the effects of MTAs on cell division but could work with particular effectiveness on brain tumor cells, underscoring the importance of developing specific inhibitors and test them in clinical trials." (PMID 34663805, 2021).
endometrial carcinoma (1 paper, 2023). A malignant tumor arising from the epithelium that lines the cavity of the uterine body. "Using 108 cases of endometrial carcinoma and 15 cases of normal endometrium, we found that the expression of KNL1 protein in tumors was higher than that in normal tissues." (PMID 36776306, 2023). "Finally, to verify the function of KNL1, this study used the endometrial cancer cell lines HEC-1-A and Ishikawa to downregulate the expression of KNL1 by stable transfection of shRNA." (PMID 36776306, 2023). "Taking into consideration the upregulation of KNL1 expression in tumor tissues and its inhibition of antitumor immunity, we speculated that KNL1 might be correlated with the prognosis of patients with endometrial cancer." (PMID 36776306, 2023).
glioma (1 paper, 2021). A benign or malignant brain and spinal cord tumor that arises from glial cells (astrocytes, oligodendrocytes, ependymal cells). "KNL1 is a type of cancer/testis antigen and has been confirmed to be highly expressed in high‐grade glioma cell lines and glioma patients, but its detailed function in glioma has not been explored." (PMID 33423377, 2021).
neurofibroma (1 paper, 2023). An intraneural or extraneural neoplasm arising from nerve tissues and neural sheaths. "Additional recurrent but low-frequency mutations in neurofibromas include FANCA, PTPRD, NF2, LZTR1, KNL1 and RUNX1." (PMID 37164978, 2023).
oligospermia (1 paper, 2023). Decreased number of spermatozoa in the semen. "Here, we first found that the loss of KNL1 caused oligospermia and asthenia in mice and detected the abnormal composition of different ploidy sperm cells by FCM." (PMID 36904774, 2023).
papillary renal cell carcinoma (1 paper, 2022). A rare subtype of renal cell carcinoma, arising from the renal tubular epithelium and showing a papillary growth pattern, which typically manifests with hematuria, flank pain, palpable abdominal mass or nonspecific symptoms, such as fatigue, weight loss or fever. "Interestingly, these KNL1-related molecules (e.g., BUB1, ASPM, TOP2A) have been implicated in immune infiltration in papillary renal cell carcinoma in another report." (PMID 36685823, 2022).
cancer (20 papers, 2002 to 2026). A tumor composed of atypical neoplastic, often pleomorphic cells that invade other tissues. "KNL1 (kinetochore scaffold 1) has attracted much attention as one of the assembly elements of the outer kinetochore, and the functions of its different domains have been gradually revealed, most of which are associated with cancers, but few links have been made between KNL1 and male fertility." (PMID 36904774, 2023). "Previous studies have shown that KNL1 plays important roles in several types of cancer, and KNL1 was found to be abnormally expressed in 16 types of cancer." (PMID 36904774, 2023). "It was reported that KNL1 was upregulated in GC tissues and contributed to the proliferation of cancer cells." (PMID 35187167, 2022). "The TIMER database findings indicated that KNL1 gene is differentially expressed in a variety of cancers." (PMID 36685823, 2022). "KNL1 was highly expressed in 31 cancer types, including LUAD." (PMID 41930176, 2026). "High KNL1 expression has been observed in all cancer cell lines available in the HPA database (accessed on 9 May 2023), of which five are from OS." (PMID 37445641, 2023). "In addition, KNL1 is involved in cell growth and division and can interact with the tumor suppressor pRb to regulate cell proliferation in cancers." (PMID 30390708, 2018). "Although previous papers described the abnormal mitosis in cancer cells treated with D40/Knl-1 siRNA9, 29, we are the first to demonstrate that D40 siRNA induced apoptosis in and inhibited the growth of cancer cell lines, not only in vitro, but also in animal experiments." (PMID 26348410, 2015). "Also, the oncogenic function of KNL1 has been validated in cancer." (PMID 32795273, 2020). "Kinetochore Scaffold 1 (KNL1), also known as CASC5, D40, and AF15Q14, is primarily expressed in healthy testicles, various human cancer cell lines, and primary malignancies." (PMID 36776306, 2023). "We identified 14 cancer driver genes, including the most frequently altered KMT2C (100%), KNL1 (100%), NCOR2 (100%), and CCDC6 (93%) genes." (PMID 34245124, 2021).
tumor (12 papers, 2002 to 2023). "Finally, KNL1 expression is associated with a variety of tumor infiltrating immune cells, especially Treg and Th2 cells." (PMID 36685823, 2022). "The expression of KNL1 protein in normal tissues is low, and the expression of KNL1 in tumor tissues gradually increases with a gradual decrease in tumor differentiation." (PMID 36776306, 2023). "Knockdown of KNL1 expression weakened cell viability and decreased the metastatic and invasive abilities of the tumor cells." (PMID 36776306, 2023). "Kinetochore scaffold 1 (KNL1) has been reported to be involved in tumor progression and prognosis in other tumors, but its role in PRAD has not been reported in detail." (PMID 36685823, 2022). "Clinical correlation analysis showed that KNL1 expression was associated with PSA level, Gleason score, tumor size, regional lymph node metastasis." (PMID 36685823, 2022). "Our group analysis results exactly showed that higher expression of KNL1 brought more Th2 and Treg infiltration, and at the same time, NK cell and other anti-tumor components showed a lower enrichment level." (PMID 36685823, 2022). "In tumor tissues, KNL1 was positively correlated with the marker genes of TAM, M2 macrophages and Tregs." (PMID 36685823, 2022). "The WES analyses detected mutations in KMT2C, KNL1, and NCOR2 genes in all the tumor samples (100%)." (PMID 34245124, 2021). "The expression of KNL1 was significantly increased in tumor tissues." (PMID 36776306, 2023). "The results showed that high expression of KNL1 led to worse OS of patients with these tumors, suggesting that KNL1 may be closely related to tumor progression." (PMID 36776306, 2023). "Additionally, targeted knockdown kinetochore scaffold 1 in tumor cells resulted in the obvious inhibition on cell phenotypes." (PMID 35933405, 2022). "Subsequently, we analyzed the expression profile data downloaded from TCGA-PRAD, and it could be seen that KNL1 gene was relatively highly expressed in tumor tissues, both in unpaired (p < .001) and paired (p < .001) samples analysis." (PMID 36685823, 2022). "The results of this study indicate that upregulation of KNL1 expression may be adverse to the antitumor immune response of the body, and it is significantly positively correlated with the immunotherapy target CD47, suggesting that KNL1 may be a potential immunotherapy target for tumor immunotherapy." (PMID 36776306, 2023). "Therefore, KNL1 can be used as a potential molecular target for tumor therapy." (PMID 36776306, 2023). "Finally, this study revealed the relationship between KNL1 expression and tumor immune invasion." (PMID 36685823, 2022). "KNL1 expression was different in patients with different FIGO stages, different tumor invasion statuses, different histologic grades, and different lymphatic metastases." (PMID 36776306, 2023). "After sorting and analyzing the expression profile data and clinicopathological parameter files in TCGA-PRAD using R software, we observed the mRNA level of KNL1 was related to PSA (ng/ml), Gleason score, tumor size, regional lymph node metastasis." (PMID 36685823, 2022). "However, immunohistochemical analysis of 108 clinical samples showed that KNL1 protein expression was correlated with FIGO stage, tumor invasion, histologic grades and lymphatic metastases of patients." (PMID 36776306, 2023). "However, KNL1 expression was not correlated with age, distant metastasis, primary therapy outcome and residual tumor." (PMID 36685823, 2022).
infection (1 paper, 2026). The state of being infected such as from the introduction of a foreign agent such as serum, vaccine, antigenic substance or organism. "Stable KNL1-knockdown and KNL1-overexpressing LUAD cell lines were established using lentiviral infection." (PMID 41930176, 2026).
KNL1 also shares sentences with these, for which no sentence is quoted: lung carcinoma (2 papers); adenocarcinoma (1); autosomal recessive primary microcephaly (1); bladder cancers (1); Colon Cancer (1); diabetic cardiomyopathy (1); dyskeratosis congenita (1); Fanconi anemia (1); glioblastoma (1); Granuloma (1); hepatocellular carcinoma (1); lymphoma (1); Lynch syndrome (1); medulloblastoma (1); melanoma (1); neuroendocrine tumors (1); neurological disorders (1); pontocerebellar hypoplasia (1); primordial dwarfism (1); prostate (1); prostate adenocarcinoma (1); rectal cancer (1); rectum adenocarcinoma (1); sarcoidosis (1); schizophrenia (1); testicular germ cell tumor (1); Type 2 Diabetes (1); uterine corpus endometrial carcinoma (1); ZIKV infection (1).